ACE (angiotensin I converting enzyme)
Diseases named in the same sentence as ACE in open-access papers (continued):
Sharing a sentence is not in itself a finding about the gene and the disease.
cancer (296 papers, 2004 to 2026). A tumor composed of atypical neoplastic, often pleomorphic cells that invade other tissues. "It would be valuable in future work to further investigate these potential mechanistic pathways in relation to ACE inhibition and increasing cancer risk." (PMID 41085561, 2026). "Population studies investigating the association of RAS inhibitor (RASi) use, ARBs, and ACE inhibitors (ACEis), with cancer incidence or survival have yielded mixed, yet mostly positive results." (PMID 41408463, 2026). "This approach is consistent with previously published work, investigating the effect of genetically proxied ACE inhibition on cancer risk." (PMID 41085561, 2026). "There is some evidence that long-term use of anti-hypertensives that reduce the activity of the RAS, such as ACE inhibitors (ACEIs) and angiotensin receptor blockers (ARBs), reduces the risk of some cancers, particularly female-specific cancers." (PMID 41303450, 2025). "Studies suggest that the altered expression of the ACE has been linked to the initiation and progression of various cancers." (PMID 40710006, 2025). "Specifically, anti-hypertensive drugs were associated with decreased cancer-specific mortality, with ACE inhibitors, beta-blockers and thiazide diuretics showing positive results." (PMID 40093321, 2025). "Although there are different results regarding carcinogenesis and its role in cancer patients, ATGIIR1 and ACE expression are thought to be associated with poor prognosis in many cancers." (PMID 39350850, 2024). "We found, that users of either ARBs or ACE inhibitors separately had lower cancer-specific death risk (HR 0.84, 95% CI: 0.47–1.51 and HR 0.59, 95% CI: 0.38–0.92, respectively)." (PMID 38439058, 2024). "The ACE rs4291 (T>A) is an alteration in the promoter region referred to confer susceptibility to cancer in the Asian and Caucasian ethnic groups and specifically to BC in Latino populations." (PMID 38785560, 2024). "Regarding the third assumption, if the genetic variation associated with ACE inhibition is related to other risk factors that affect cancer development, then the pleiotropic effect of the SNP should yield a positive result." (PMID 37799968, 2023). "Angiotensin-converting enzyme (ACE) gene polymorphism is one of the most studied genetic systems in recent years, including cardiovascular, metabolic, immune, cancer, aging, neurodegenerative diseases and mental illness." (PMID 37371643, 2023). "When analyzing epidemiological data on the effect of RASIs on cancer, ACE polymorphisms including the insertion/deletion (I/D), which influences the expression of ACE, should be considered." (PMID 35574555, 2022). "There was little evidence to support associations of genetically proxied ACE inhibition with risk of other cancers." (PMID 35113855, 2022). "Other drugs, when administered concomitantly with certain cancer drugs, such as diuretics, angiotensin-converting enzyme (ACE)-inhibitors, or proton-pump inhibitors, are associated with increased toxicity." (PMID 35269781, 2022). "Later on, in a randomized, double blind, placebo-controlled trial, ACE inhibitors were shown to prevent weight loss in heart failure patients, indicating the putative role of AngII in cancer-induced cardiac cachexia." (PMID 35326441, 2022). "A meta-analysis of studies of the association of the DD and II ACE genotypes, a variety of cancers, suggested that the II ACE genotype was weakly associated with reduced risk of some cancers." (PMID 34285715, 2021). "There is considerable variance in the reported effects of ACE inhibitors on cancer risk with some studies of CRC showing a chemoprotective effect." (PMID 34285715, 2021). "A retrospective cohort study showed that the use of ACE inhibitors has an association with a clearly decreased risk of overall cancer." (PMID 29514670, 2018).
cancer (continued). "Of note the previous study compared ARB + ACE inhibitor treated groups compared to ACE inhibitor only groups to show the association of ARB use with increased cancer risk." (PMID 28791183, 2017). "The first evidence for the antitumor effects of ACE blockers was demonstrated in 1998 in which the relative risk of fatal, incident and female-specific cancers was lower in women on ACE inhibitors." (PMID 27992423, 2016). "In 1998, an observational study first demonstrated that hypertensive patients taking ACE inhibitors had a reduced cancer risk compared with patients in the control group (RR 0.72, 95 % CI 0.55–0.92)." (PMID 27646033, 2016). "In order to resolve this issue, we conducted a meta-analysis of 25 case-control studies, including 3914 cases and 11391 controls, to evaluate the associations between the ACE I/D polymorphism and cancer risks." (PMID 22151803, 2011). "The aim of this study is to assess the association between the I/D polymorphism in the ACE gene and cancer risk by meta-analysis." (PMID 22151803, 2011). "Based on past studies in this population and others, it is unlikely that calcium antagonists or beta blockers, or ACE inhibitors are associated with cancer." (PMID 15812478, 2005). "However, functions of ACE and the renin-angiotensin system have also been linked to cancer, tumor microenvironment, and (cancer) immunity." (PMID 40235590, 2025). "Furthermore, potentially bioactive peptides associated with ACE inhibitory, anti-hypertensive, anti-cancer, antimicrobial, antiviral, antithrombotic, DPP-IV inhibitory and PEP-inhibitory activities were identified in CAMC." (PMID 38914602, 2024). "Future evaluation of the potential effects of long-term ACE inhibitor use on cancer risk should therefore include assessment of whether findings are specific to individual agents or classes of ACE inhibitors." (PMID 35113855, 2022). "ACE inhibitors and ARBs might be carcinogenic as both increase the risk of cancer when compared to the placebo." (PMID 36005423, 2022). "One previous meta-analysis had suggested that the excess risk of cancer with ARBs may be limited to patients with concurrent ACE-inhibitor treatment." (PMID 35235571, 2022). "Second, several studies examining ACE inhibitor use and cancer risk have included prevalent drug users, which can introduce bias because prevalent users are “survivors” of the early period of pharmacotherapy and because covariates at study entry can be influenced by prior medication use." (PMID 35113855, 2022). "Therefore, future research is necessary to determine the association between ACE polymorphism, ACE levels, and cancer risk." (PMID 33579229, 2021). "Studies have previously demonstrated that established therapies, particularly ACE inhibitors and ARBs, have a role in reducing the risk of cancers, improving cancer survival outcomes, delaying progression of invasive cancers, and decreasing the quantity of tumor metastasis." (PMID 34285715, 2021). "Notably, ACE expression was strongly connected with macrophages and cancer-associated fibroblasts (CAFs) in most tumors and was more related to M2-type macrophages." (PMID 34671200, 2021). "Although ACE inhibitors are relatively safe for short-term use, an increased risk of cancer may be associated with ACE inhibitors for long-term use." (PMID 32121598, 2020). "Epidemiological data have suggested that long-term use of ACE inhibitors may decrease the risk of cancer in high-pressure patients, although these results were contradictory." (PMID 32581212, 2020). "Moreover, future studies should also investigate gene-gene and gene-environment interactions to better display the association between the polymorphisms in ACE gene and cancer risk." (PMID 22151803, 2011). "Thus, future studies are warranted to identify the associations between ACE polymorphism, ACE levels and cancer risk." (PMID 22151803, 2011).
cancer (continued). "Second, this is a comprehensive meta-analysis concerning cancer risk and ACE D/I polymorphism and the result also indicated a gene in RAS may not contribute to cancer risk." (PMID 22151803, 2011). "Therefore, contemporary guidelines provide a Class IIa recommendation for the use of ACE inhibitors or ARBs and beta-blockers as primary prevention therapy in high-risk cancer patients receiving oncological therapies that may increase the risk of HF." (PMID 37886969, 2023). "The interindividual variation in ACE levels in blood and tissues is mainly due to a common polymorphism in the ACE gene consisting of the insertion (I) or deletion (D) of a 287-bp fragment; moreover, it has been associated with risk for several diseases, including cancer." (PMID 35804826, 2022). "Inhibition of ACE activity suppresses tumor growth and angiogenesis in vitro and vivo of animal models; moreover, epidemiologic studies have also indicated that ACE inhibitors might decrease the risk and mortality rate of cancers." (PMID 22151803, 2011). "Subsequently, we employed a univariate Cox regression model to analyze the association between the expression levels of ACE and HSPB8 in pan-cancer samples and patient survival." (PMID 41490177, 2026). "RAS components, including angiotensin-converting enzyme (ACE), Ang II, and angiotensin receptors (AT1R and AT2R), are expressed in various cancer tissues and have been implicated in tumorigenesis." (PMID 40940839, 2025). "In silico analysis of FDA-approved drugs led to the identification of an ACE inhibitor, ramipril, that protected against sunitinib-induced vascular dysfunction in vitro and in vivo, all while preserving the efficacy of cancer therapy." (PMID 39895626, 2025). "The fermentation of milk by L. helveticus significantly enhances the production of bioactive peptides, including antioxidant peptides, angiotensin-converting enzyme (ACE) inhibitors, as well as anti-cancer and anti-inflammatory peptides." (PMID 40686900, 2025). "ACE inhibitors and β-blockers tend to reduce cancer-related mortality, whereas CCBs and diuretics have been reported to have the opposite effect." (PMID 41134847, 2025). "So far, β-blockers, ACE inhibitors, and ARBs have been the most commonly evaluated antihypertensive agents in the context of cancer, while thiazide and thiazide-like diuretics have been less studied." (PMID 40093321, 2025). "The impact of ACE inhibitors (ACEi) and angiotensin receptor blockers (ARBs) on cancer risk and treatment outcomes has been a subject of debate." (PMID 40235590, 2025). "Altering ACE expression and its resulting immune stimulation provides an exciting opportunity for alternative immunotherapy and treatment of infections, cancer, and other metabolic disorders." (PMID 39000163, 2024). "There are studies exploring the use of beta-blockers, ACE inhibitors, or ARBs as preventative treatments for cancer patients to reduce cardiotoxicity." (PMID 38832203, 2024). "This strategy allowed for the timely initiation of ACE inhibitors and beta-blockers, which are crucial for mitigating severe cardiac dysfunction and maintaining optimal cardiac function during and after cancer therapy." (PMID 39238728, 2024). "Marching into the forefront of scientific exploration, recent advancements have unveiled unexplored pathways in ACE inhibition, surpassing traditional remedies and extending into interactions within cancer therapies." (PMID 38543146, 2024). "Elevated ACE levels confer significant advantages for certain cancers while being detrimental to others." (PMID 39635438, 2024). "ACE 10/10 mice show significantly improved resistance to atherosclerosis, cancer progression, Alzheimer’s disease, and bacterial infections." (PMID 39000163, 2024). "Regarding malignancies management, ACE inhibition has been noted to have implications in cancer treatment, particularly in the context of radiotherapy." (PMID 38543146, 2024).
cancer (continued). "Patients with cancer had significantly lower use of ACE (angiotensin-converting enzyme) inhibitors/angiotensin receptor blockers (mean percentage point decrease [mppd], 2.6% [95% CI, 1.8–3.4]) and lower overall composite care (mppd, 1.2% [95% CI, 0.9–1.6])." (PMID 37339190, 2023). "Ongoing research is exploring the potential benefits of administering beta-blockers, ACE inhibitors, or angiotensin receptor blockers (ARBs), as preventive measures to avoid cardiotoxicity in patients undergoing cancer treatment." (PMID 37533611, 2023). "Key guideline-based medical therapies such as antiplatelet therapies, ACE inhibitors, or angiotensin receptor blockers and use of statins were used less frequently in patients with a prior cancer diagnosis." (PMID 37339190, 2023). "According to the BIOPEP database, the peptide HIQKEDVPSER in FR1 is considered an antioxidant peptide, and FFVAPFPEVFGK in FR2 is a known angiotensin-converting enzyme (ACE) inhibitor and anti-cancer peptide." (PMID 38201040, 2023). "Bioactive peptides derived from walnut protein have been suggested to possess various biological functions, such as ACE-inhibitory activity, antioxidant activity, and anti-cancer activity, which were attributed to the amino acid compositions and sequences." (PMID 37048311, 2023). "Other preventive measures are modifications of cancer therapy dose and administration method and the administration of potentially cardioprotective drugs such as beta-blockers and or ACE inhibitors or ARBs." (PMID 35492815, 2022). "In previous studies patients who received VEGF-targeted therapy were reported to have improved cancer-specific survival when targeted therapy was combined with ACE-inhibitors or other RAS targeting active substance." (PMID 34921656, 2022). "A retrospective cohort study conducted on 5207 hypertensive patients in Scotland reported that the prolonged use of angiotensin-I-converting enzyme (ACE) inhibitors showed a protective role against cancer." (PMID 35326441, 2022). "Subsequently, various protein hydrolysates subjected to plastein reaction were observed with enhanced activities to inhibit ACE, scavenge free radicals, or inhibit the growth of cancer cells." (PMID 35053927, 2022). "An important fact is that ACE inhibitors, ARBs, and b-blockers cannot be used for a long time in cancer patients." (PMID 36005423, 2022). "Components of the RAS, i.e., renin, pro-renin receptor (PRR), angiotensin-converting enzyme (ACE), ACE2, angiotensin II receptor 1 (AT1R), and angiotensin II receptor 2 (AT2R), have been associated with the development of cancer." (PMID 33916968, 2021). "The positive effects of ACE inhibitors and BB were recently evaluated in clinical trials in cancer patients." (PMID 34409077, 2021). "ACE can inactivate bradykinin; however, low levels of ACE in tumor tissues can promote the invasive growth of malignant tumors." (PMID 33579229, 2021). "Variant expression of ACE, ACE2, and AGT was correlated with corresponding E3 ligase expression in cancer." (PMID 34671200, 2021). "This food has been reported for its potential pharmacological properties, including antibacterial, anti-cancer, anti-inflammatory, angiotensin-converting enzyme (ACE) inhibition, immunomodulatory effects, and use in tissue engineering applications." (PMID 34976961, 2021). "The oncoprint displayed an overall alteration frequency of RAS family of 15.2% in TCGA pan-cancer across TCGA cancers, with the highest frequency existing for ACE (4%), followed by AGT (3%), AGTR1 (3%), ACE2 (2.3%), AGTR2 (1.5%) and MAS1 (1.4%)." (PMID 34671200, 2021). "The insect bioactive peptides and lipids have beneficial effects on human health, such as antioxidant, antimicrobial and antidiabetic properties, angiotensin I converting enzyme (ACE) inhibition activity, effects against inflammation and cancer." (PMID 33717009, 2021).
cancer (continued). "Genomic alterations of the RAS family were infrequent across TCGA pan-cancer program, and ACE had the highest alteration frequency compared with other members." (PMID 34671200, 2021). "Lastly, we would like to emphasize that tumor samples are heterogeneous and ACE gene expression in tumors not only came from cancer cells but also stromal cells." (PMID 33858332, 2021). "After drug administration, the content was increased in the cancer-bearing mice; in particular, the high dose of ACE showed a significant upregulation (p < 0.05)." (PMID 34531745, 2021). "ACE inhibitors were evaluated in the clinic and reported to improve outcomes for radiation-induced pneumonitis in cancer patients." (PMID 34079456, 2021). "ACE expression in cancer cell lines was positively correlated with the IC50 value of bleomycin in those cell lines, suggesting that higher ACE expression in cancer cell lines is associated with higher resistance to bleomycin." (PMID 33858332, 2021). "Guidelines currently do not recommend routine concomitant use of cardioprotective drugs (i.e., statins, ACE inhibitors, ARBs, BB) with potentially cardiotoxic cancer therapies." (PMID 34406595, 2021). "ACE2 has been investigated also as cancer marker, as it has been observed an increase of ACE2 expression in thyroid cancer with an increase of ACE2/ACE ratio proportional to the differentiation grade of the cancer." (PMID 33344479, 2020). "In vitro and in vivo studies showed that activation of the ACE/Ang II/ angiotensin II type 1 receptor (ATR1) axis promotes cancer cell proliferation, invasion, angiogenesis and reduced immunosurveillance." (PMID 33353148, 2020). "Angiotensin I converting enzyme (ACE) insertion (I) and 287 bp Alu repeat DNA fragment deletion (D) polymorphisms have been indicated in various cancers." (PMID 32089890, 2020). "Just recently, it has been established that the angiotensin-converting enzyme (ACE) insertion/deletion (I/D) polymorphism is linked to the pathogenesis and to the evolution of human cancers." (PMID 31312309, 2019). "The results in the Rotterdam study concerning a prospective cohort with 7983 participants, showed that RAS inhibitors seemed to protect against cancer in patients with the ACE DD genotype." (PMID 31312309, 2019). "For example, while multiple clinical trials in adults have reported a benefit with ACE inhibitors, there are very few pediatric trials in cancer patients with mixed results." (PMID 32154022, 2019). "In a Dutch population based prospective cohort study that included 6670 participants with ACE genotype, 730 incident cancer cases occurred during a mean follow-up time of nearly ten years." (PMID 31312309, 2019). "The alcalase hydrolysates of MBVP under in-vitro conditions showed to be efficient free radical scavengers, having antiproliferative activity against cancer cell line and also ACE inhibitors." (PMID 29408872, 2018). "There were also significant increases in the use of statin, β-blocker, and ACE-inhibitor medications in the cancer group." (PMID 29799976, 2018). "Recent reviews have highlighted the emerging role of the RAS in regulating tumor growth and angiogenesis in experimental cancer models as revealed by angiotensin-converting-enzyme (ACE) inhibitors and angiotensin receptor blockers (ARBs)." (PMID 30103733, 2018). "A recent meta-analysis of RAS blockade with ACE inhibitors and/or ARBs suggested that RAS blockade reduces cancer risk." (PMID 28791183, 2017). "Since both ACE inhibitors and ARBs are widely used antihypertensive agents, meta-analyses have been conducted to identify any correlation for cancer incidence in patients taking these drugs and/or the effects of these drugs on cancer risk." (PMID 28791183, 2017). "Nevertheless, aspirin and beta-blockers have advanced to randomized clinical trials (RCTs) to confirm their anti-tumor effects, while findings have been inconsistent with regard to cancer and ACE inhibitors, ARBs, cardiac glycosides or statins." (PMID 27646033, 2016).